MMP1 (matrix metallopeptidase 1)
Diseases named in the same sentence as MMP1 in open-access papers (continued):
Sharing a sentence is not in itself a finding about the gene and the disease.
infection (continued). "Using these two infection models, we confirmed that the transcription levels of KLK12, MMP-1, and MMP-9 in lung tissue were positively correlated with the initial dose of infection." (PMID 36293113, 2022). "ELISA kits were used to detect serum levels of KLK12, MMP-1, and MMP-9 in mice with different infection doses, and the results were consistent with findings in lung tissues." (PMID 36293113, 2022). "Six out of eight proteins were significant in the longitudinal analysis for at least one effect (time [ITGB1BP2, AXIN1, MMP1, STAMBP] or condition [GH, ITGB1BP2, 4E-BP1]), suggesting their importance both during hospitalization and after infection." (PMID 36405747, 2022). "We then examined the expression levels of KLK12 and MMP-1/-9 in RAW264.7 cells infected with NTMs and observed that MAP and M. smegmatis infection only upregulated MMP-1/-9 but downregulated KLK12." (PMID 36293113, 2022). "A significant reduction in the expression of MMP-1 and MMP-9 was observed in KLK12 knockdown RAW264.7 cells at 24h post-infection with M. bovis compared to control cells." (PMID 36293113, 2022). "Using qRT-PCR, these researchers showed that this reduction was vhs dependent based on two sets of genes that exhibited either high (COL6A2, MMP3, and MMP1) or low (GAPDH, ACTB, and RPLP0) reduction in total RNA levels in WT infection." (PMID 33148793, 2021). "All three collagenases (MMP1, MMP13 and CTSK) tested demonstrated increased expression in response to infection." (PMID 34805001, 2021). "A significant increase in the expression of MMP1, MMP3, MMP9, MMP12, MMP13, and MMP14, was noted in Mtb-AG infected, compared with Mtb-SC-infected rabbit lungs, at both 1 and 4 weeks post infection." (PMID 34732811, 2021). "The hypersensitive MMP1 and MMP3 transcripts underwent slow degradation in CHX-treated cells, but as early as 2 hours after infection this was enhanced during active infection (central panel)." (PMID 30475899, 2018). "After infection, particularly at the 6 h and 8 h time points, CSF2, CCL2, MMP1, and MMP10 proteins were expressed at higher levels in CF than CTRL cells, although the differences were not statistically significant." (PMID 26485688, 2015). "The expression of MMP-1 and MMP-10 was significantly upregulated following induction by H. pylori infection (P<0.05), with significant effects occurring following infection for 12 and 6 h, respectively." (PMID 25120597, 2014). "Upon further investigation, we found that specific cytokines, chemokines and growth factors could be correlated with subsequent infection: IL‐10, IL‐31, ENA‐78, fractalkine, MCP‐2, HGF and MMP‐1." (PMID 40766049, 2025). "During infection or injury, GBP1 reduces endothelial cell proliferation by downregulating matrix metalloproteinase 1 (MMP1) and upregulating integrin-alpha 4, stabilizing tissue barriers and preventing excessive breakdown—a critical anti-inflammatory mechanism." (PMID 40564939, 2025). "Serum KLK12, MMP-1, and MMP-9 were significantly upregulated in mice after M. bovis infection, and the degree of upregulation was positively correlated with the initial infection dose." (PMID 36293113, 2022). "The analysis of the fibroblasts revealed that the PAOX expression significantly increased the MMP-1 secretion compared with that of the infection with the control virus and mock infection, but it did not significantly affect the type I collagen secretion." (PMID 36142401, 2022). "In the case of MMP1 and MMP3, these transcripts were reduced by log2 change of 8 in WT infection, again but these transcripts were only slightly reduced in the HSV1 vhs-GFP infection compared to the mock-infected control at 16 h." (PMID 35758691, 2022). "Vitamin D therapy of PBMCs decreases the MMP-10, MMP-1, and MMP-7 expression while increasing the TIMP-1 expression, indicating its critical function in preventing cellular injury and providing symptom relief while having an infection." (PMID 34944659, 2021).
infection (continued). "Likewise, matrix metallopeptidase 1 (MMP1), MMP2, and MMP14 were significantly up-regulated while the transcript of MMP11 was repressed by infection." (PMID 27197554, 2016). "Similarly, we also found an up regulation of tissue remodeling factors induced by extracellular infection with WCH-SK2WT (MMP1, MMP2, and MMP10) and WCH-SK2SCV (MMP1 and MMP9) as well as intracellular infection with WCH-SK2WT (MMP9)." (PMID 28083514, 2016). "Although nothing is known about the role for MMP1 or MMP10 in CF, our data suggest that these two enzymes may be involved in tissue damage related to excessive inflammation and may contribute to infection-related CF pathology." (PMID 26485688, 2015). "Thus, an imbalance between the circulating levels of specific MMPs and TIMPs—especially increased MMP-1 and MMP-8 to TIMP-4 and decreased MMP-1 and MMP-7 to TIMP-1 and 2—is characteristic of filarial lymphedema in the presence of active infection." (PMID 22679524, 2012). "In a previous study investigating the direct infection of human macrophages with Mtb, other stimuli such as LPS, BCG, and individual cytokines including TNF‐α, IL‐1β or IFN‐γ did not drive MMP‐1 production." (PMID 29210073, 2018).
cardiovascular disease (20 papers, 2011 to 2025). "MMP1 is implicated in the pathogenesis of atherothrombotic cardiovascular disease." (PMID 23497408, 2013). "In cardiovascular diseases, increased MMP1 expression in the heart led to a disruption of structural collagen and cardiac dysfunction." (PMID 37006258, 2023). "Participants with high risk for cardiovascular disease displayed increased serum levels of several factors secreted by senescent cells, including FXIV, MMP1, and C5A." (PMID 37097759, 2023). "Among these associated protein-coding genes, MMP1, CTSB, POMC, RETN, and IL6R are known to be associated with SCAD or other cardiovascular diseases." (PMID 35425820, 2022). "Among the identified MMPs, MMP-1, -2, -3, -9, and -14 attracted more attention regarding their relation to cardiovascular disorders." (PMID 32466129, 2020). "In this study (in a subgroup of non-diabetics, n = 515) it was shown that serum levels of MMP-7 and -12 were significantly elevated in subjects with signs of cardiovascular disease (n = 270) whereas levels of MMP-1,-3 and-10 were unaffected." (PMID 30789935, 2019). "We investigated associations between plasma MMP-1, −2, −3, −9, −10 and TIMP-1, and cardiovascular disease (CVD) or microvascular complications in type 1 diabetic patients." (PMID 25848912, 2015). "Rupture of an atherosclerotic plaque is a key event in the development of cardiovascular disorders, in which matrix metalloproteinase-1 (MMP-1) plays a crucial role by degradation of extracellular matrix resulting in plaque instability." (PMID 23935888, 2013). "Some peripheral cytokines frequently studied in cardiovascular disease such as matrix metalloproteinase-1 (MMP-1), matrix metalloproteinase-3 (MMP-3), osteopontin, and pentraxin-3 can be used as markers to reflect vascular inflammation, endothelial function, or permeability of the BBB." (PMID 38581060, 2024). "Furthermore, many of the age-associated proteins such as CST5, CCL23, SLAMF1, MMP-1, MCP-1, and CDCP1 have been linked to chronic diseases such as cardiovascular disease and neurocognitive decline in the general population." (PMID 37672793, 2023). "Thus, further studies may be necessary to elucidate the role of MMP1 SNPs/levels in the development of cardiovascular disease." (PMID 23497408, 2013). "The correlation between the increase in the expression level of MMP-1, MMP-3, and MMP-12 and plaque instability and cardiovascular disease progression were demonstrated clearly." (PMID 32466129, 2020). "The fact that TIMP-1 is the inhibitor also of other MMPs than MMP-9 (notably MMP-1), and these MMPs may also be important in the pathophysiology of cardiovascular disease, may partly explain why TIMP-1 was a stronger marker than MMP-9 of cardiovascular disease risk in this and other studies." (PMID 21283828, 2011).
adenocarcinoma (9 papers, 2008 to 2025). A common cancer characterized by the presence of malignant glandular cells. "The expression of MMP-1 was significantly related when comparing the mucinous histological type with NOS adenocarcinoma (p = 0.00 and fold change of 1.57) and with the presence of peritumoral inflammatory infiltrate (p = 0.01 and fold change of −1.84)." (PMID 32813775, 2020). "Results of the present in vitro study, including initial microarray analyses, demonstrate that MMP-1 expression is more significantly increased in EGFR-TKI–resistant adenocarcinoma cells than in EGFR-TKI–sensitive cells." (PMID 29463039, 2018). "There was a clear co-upregulation of PEA3 and ER81 with MMP-1 and, to a lesser extent, MMP-7 in adenocarcinoma samples, suggesting a causative role for PEA3 subfamily members in driving MMP-1 expression." (PMID 21143918, 2010). "RT-PCR results for MMP-1 expression in the adenocarcinoma cell line OE-33 showed a 4.1-fold higher expression compared to normal tissue." (PMID 20946664, 2010). "Importantly, the majority of samples that showed increased levels of both a PEA3 family member and MMP-1 were derived from adenocarcinomas." (PMID 21143918, 2010). "We therefore examined whether P-ERK levels and PEA3 subfamily expression in adenocarcinoma samples might correlate with the expression of a key driver of metastasis, MMP-1." (PMID 21143918, 2010). "The expressions of MMP-1 and MMP-2 have shown a statistical correlation to the mucinous histological type with signet ring cells when compared to NOS adenocarcinoma." (PMID 32813775, 2020). "In adenocarcinoma tissue, the co-occurrence of PEA3 family member expression correlates with enhanced MMP-1 expression." (PMID 21143918, 2010). "MMP-1 is identified as an important target for PEA3 subfamily members in cell line models and is co-expressed with these transcription factors in human adenocarcinomas." (PMID 21143918, 2010). "Together these results therefore establish OE33 cells as a useful model to study PEA3 function in adenocarcinoma cells as they express both PEA3, and its target gene MMP-1." (PMID 21143918, 2010). "In the present study, both the gene and protein expression of MMP-1 have shown a statistical correlation with the histological type, with greater expression in mucinous types with signet ring cells than in the NOS adenocarcinoma type, suggesting that it is related to malignancies of worse prognosis." (PMID 32813775, 2020). "For adenocarcinomas without BE, the results of MMP-1 expression were comparable with the higher expression levels of adenocarcinomas from BE." (PMID 20946664, 2010).
bacterial infection (5 papers, 2019 to 2025). "In diabetic dermis, the upregulation of CTSG, MMP9, and MMP1 may depend on bacterial infection at the site of DFU and on a dysregulation of growth factors." (PMID 31315286, 2019). "Similarly, the levels of MMP1 produced by GFs cultured with DAC were significantly higher compared to DMSO-treated cells regardless of the absence or presence of cytokine stimulation or bacterial infection." (PMID 36776856, 2023). "In previous studies, bacterial infection and Imd signalling was shown to stimulate JNK-mediated Mmp1 expression in the hindgut facilitating cell dissemination by RasV12." (PMID 40476337, 2025). "After bacterial infection, however, Mmp1 staining in EEs increases, supporting the notion that Mmp1 expression is increased in EEs after injury." (PMID 34887411, 2021).
diseases of the immune system (3 papers, 2014 to 2025). "For example, ADAM8 and MMP-1 are implicated in T-cell maturation and ECM remodeling, while cathepsins, UPA, and PC9 contribute to immune dysfunction and aging." (PMID 41208973, 2025).
inflammation (3 papers, 2021 to 2026). Aberrant reaction of the microcirculation characterized by movement of fluid and leukocytes from the blood into extravascular tissues. "In COPD patients, MMP1 expression is also increased, possibly due to its ability to activate inflammatory cells and promote the release of inflammatory factors, thereby exacerbating pulmonary inflammation." (PMID 40002743, 2025). "In this context, epistatic interactions between MMP1, IL10, and IL17A are biologically plausible, as excessive extracellular matrix degradation, impaired anti-inflammatory regulation, and enhanced Th17-driven responses may act synergistically to promote chronic periapical inflammation." (PMID 41614937, 2026).
neurodegenerative disease (3 papers, 2012 to 2022). A disorder of the central nervous system characterized by gradual and progressive loss of neural tissue and neurologic function. "Evidence has been generated providing insight into the transcriptional regulation of the MMP-1 promoter in response to cigarette smoke exposure, which could have a significant impact on the understanding of many age-associated degenerative disease processes." (PMID 22992122, 2012). "Protease activated receptor-1 (PAR-1) and its ligand, matrix metalloproteinase-1 (MMP-1), are altered in several neurodegenerative diseases." (PMID 30385861, 2018).
connective tissue disorder (2 papers, 2014 to 2018). A disease involving the connective tissue. "IPA demonstrated the involvement of relevant genes (OPN, POSTN, MMP-1, MMP-7, Prominin-1, and others) in the network “connective tissue disease, organismal injury and abnormality”, and other functions related to cell movement and connective tissue disorder." (PMID 30111332, 2018).
kidney disease (2 papers, 2024 to 2025). "We also found, using the Olink proteomic platform, that TNF-α and TMAO enhanced the secretion of additional inflammatory-and growth mediators associated with kidney disease; VEGFA, GDNF, CDCP1, OPG, uPA, AXIN1, MMP-1, MMP-10, PD-L1, HGF, Flt3L, 4E-BP1, CD40, CASP-8, ADA, TNFRSF9, TWEAK44–61." (PMID 38643262, 2024).
metabolic disorders (2 papers, 2019 to 2020). "Moreover, mRNA expression of TIMP-1 and MMP-1 was separately down- and upregulated, respectively, indicating that the collagen metabolism disorder had been controlled." (PMID 31534523, 2019).
musculoskeletal disease (2 papers, 2024). "Some of the prominent MMPs involved in musculoskeletal disease are MMP-1, MMP-3, MMP-9, MMP-13, and MMP-14." (PMID 38790904, 2024).
retinopathies (2 papers, 2015 to 2022). "Other interacting partners of MMP9 included fellow members of the MMP family such as MMP1, -2, -3 and -14, where links with retinopathies have already been discussed." (PMID 36498929, 2022). "Linear regression analysis was applied to investigate differences in plasma levels of MMP-1, −2, −3, −9, −10, and TIMP-1 between patients with and without CVD, albuminuria or retinopathy." (PMID 25848912, 2015).
bone disorder (1 paper, 2023). "We found a stable profile of mRNA expression for MMP-2 and 3, TIMP-2 and -3, and a slight decline for the MMP-1 and TIMP-1 and -2 profiles during the differentiation of ASCs to osteocytes, which predispose these cells to future therapy in bone disorders." (PMID 37428795, 2023).
disorders of the central nervous system (1 paper, 2015). "MMP-1 levels may also be increased in disorders of the central nervous system characterized by glial activation." (PMID 26783471, 2015).
MMP1 also shares sentences with these, for which no sentence is quoted: chronic periodontitis (12 papers); acute myocardial infarction (4); colorectal (4); tongue cancer (4); chorioamnionitis (3); colon (3); lumbar disc herniation (3); prostate adenocarcinoma (3); respiratory diseases (3); angiosarcoma of the skin (2); benign prostatic hyperplasia (2); benign tumors (2); chronic kidney disease (2); congestive heart failure (2); coronary atherosclerosis (2); essential hypertension (2); gastritis (2); inflammatory skin disease (2); injury (2); leukoplakia (2); metastatic colorectal cancer (2); mitral valve disease (2); multiple sclerosis (2); oral lichen planus (2); pancreatic adenocarcinoma (2); polymyositis (2); pulmonary hypertension (2); small vessel stroke (2); unstable angina (2); xeroderma pigmentosum (2).
A further 142 diseases each share a sentence with MMP1 in 1 paper.